ACTB (actin beta)
Diseases named in the same sentence as ACTB in open-access papers (continued):
Sharing a sentence is not in itself a finding about the gene and the disease.
cancer (114 papers, 2007 to 2025). A tumor composed of atypical neoplastic, often pleomorphic cells that invade other tissues. "Among these genes, we observed a large number of cancer‐related genes, such as ACTB (encoding β‐actin), IMMT (encoding inner membrane mitochondrial protein), and PFDNs (encoding Prefoldin)." (PMID 41312091, 2025). "A pan-cancer study of ACTB of patient cancer data has illustrated that its upregulation is associated with EMT40." (PMID 38233507, 2024). "ACTB is generally upregulated in most tumor cells and tissues, being associated with the invasiveness and metastasis of cancers." (PMID 39061201, 2024). "It has been found that ACTB is aberrantly expressed in cancer and paracancerous tissues, ACTB expression is associated with immune cell infiltration and altered immune function." (PMID 37335738, 2023). "The abnormal expression and polymerization of ACTB have been associated with cancer invasiveness and metastasis." (PMID 35765478, 2022). "The mRNA of ACTB is cytoplasm-localized and encodes a housekeeping cytoskeleton protein and the nucleus-localized hTERC RNA is associated with cancer cell proliferation." (PMID 35061906, 2022). "As a result, ACTB was positively correlated with infiltration levels of cancer associated fibroblasts (CAF), macrophages, endothelial cells and monocytes." (PMID 34486492, 2021). "The aza-steroidal alkylators, ASA-A, ASA-B and ASA-C induced a conspicuously higher increase of the PARP1/ACTB mRNA ratio in the UWB1.289 + BRCA1 than in the BRCA1 mutated UWB1.289 cancer cells." (PMID 34440232, 2021). "Differential expression of ACTB was found between cancer and adjacent normal tissues, and significant associations was found between ACTB expression and prognosis of tumor patients." (PMID 34486492, 2021). "In most cancers, ACTB expression was associated with immune cells infiltration, immune checkpoints and other immune modulators." (PMID 34486492, 2021). "We observed a significant correlation between ACTB expression and the immune infiltration level of cancer associated fibroblasts, macrophages, endothelial cells, monocytes and CD8 + T-cells in most cancers." (PMID 34486492, 2021). "The cancer patients were divided into high-ACTB-expression and low-ACTB-expression groups and the association of ACTB expression with the patient prognosis in multiple cancers was explored based on TCGA and GEO datasets." (PMID 34486492, 2021). "Studies in recent years have shown that ACTB is associated with immune infiltration in cancers." (PMID 40299520, 2025). "Because ACTB encodes a structural protein of cytoskeleton as an indispensable component of the cytoskeleton in the cell for cell migration, cell division, and regulation of gene expression, change of ACTB expression is associated with cancer and changes in response to external stimuli." (PMID 35507843, 2022). "ACTB is deregulated in multiple cancers and the resulting alterations to the cytoskeleton caused by altered expression and polymerization of ACTB have been proposed to be associated with the invasiveness and metastasis of cancers." (PMID 32349449, 2020). "The aberrant expression and aggregation of ACTB and alterations in the cytoskeleton are associated with cancer aggressiveness and metastasis, suggesting that ACTB may be expressed at different levels in different environments and under different experimental conditions." (PMID 33795012, 2021). "This analysis revealed that IQGAP1, FLNB, and ACTB are involved in the “Proteoglycans in cancer” pathway, IQGAP1, ABI2, and ACTB are associated with the “Regulation of actin cytoskelet”, IQGAP1 and ACTB are linked to the “Adherens junction”." (PMID 40672380, 2025). "ACTB is differentially expressed and plays a significant role in several human diseases, particularly cancer." (PMID 39329952, 2024).
cancer (continued). "Most signaling pathways in pan-cancer, including ACTB, FLNA, MYH9, MYH10, and TLN1, exhibited high activation levels in the epithelial-mesenchymal transition (EMT) pathway, but consistent inhibition of the cell cycle, DNA damage response, and hormone AR." (PMID 38862242, 2024). "The identification of ACTB, ACTN4, INF2, and MYL6 as DEDRGs that are implicated in both PD and various cancer types opens up exciting possibilities for developing novel therapeutic strategies for human patients." (PMID 39329952, 2024). "In pan-cancer, the high expression of ACTB, ACTN4, and MYL6 in GBMLGG, LGG, MESO, and LAML had a poor prognosis, and the high expression of INF2 in LIHC, LUAD, UVM, HNSC, GBM, LAML, and KIPAN had a poor prognosis." (PMID 39329952, 2024). "Mutations in Arp module subunits, ACTB and ACTL6A/B, were nearly selectively enriched in NDDs, whereas mutations in the helicase domain of SMARCA4 were more enriched in cancer." (PMID 37500730, 2023). "Shared recurrent mutations in both NDD and cancer included those localized to the C-terminal domain of SMARCB1, the SMARCA4 N terminus, as well as within PBRM1 and ACTB subunits." (PMID 37500730, 2023). "Our results brought to light the unstable expression of ACTB in NSCLC, making the role of ACTB as a cancer reference gene challenging." (PMID 36232605, 2022). "Seven reference genes (YWHAZ, GNAS, GAPDH, OAZ1, PTMA, B2M, and ACTB) were screened out among the 95 candidate reference genes from the data set of the platelets’ transcriptome of pan-cancer and 73 commonly known reference genes." (PMID 35770000, 2022). "Only three genes—ACTB, CSF3R, and GATA2—were identified in both the DEA and mutational analysis, which highlights their possible significance in cancer and disease development." (PMID 36497424, 2022). "The overall results indicated that GAPDH, B2M, and ACTB were more stable in each cancer than the other four candidate genes." (PMID 35770000, 2022). "A study by the Cancer Research Institute found that ACTB is the best reference gene for quantification in some cancer tissues." (PMID 36467891, 2022). "Eventually, seven ATPCR encoding genes, including ATRX, CHD5, CHD7, SMARCA4, SMARCA2, EP400, and ACTB, were identified as driver genes by at least two algorithms in certain cancer types." (PMID 35789070, 2022). "The endogenous reference gene ACTB Ct in the test set for stage IV samples ranged from 16.0 to 27.8, and in the normal samples ranged from 21.0 to 27.4; the difference between cancer and normal was statistically significant (Mann–Whitney P < 0.0001)." (PMID 36046124, 2022). "The role of ACTB for prognosis and immune regulation across 33 tumors was explored based on the datasets of gene expression omnibus and the cancer genome atlas." (PMID 34486492, 2021). "ACTB expression was increased in various cancers and high expression of ACTB was correlated with poor patient prognosis in different cancers." (PMID 34486492, 2021). "On the other hand, POPA was the best augmenter of the PARP1/ACTB mRNA ratio in BRCA1-null UWB1.289 cancer cells." (PMID 34440232, 2021). "The KEGG results showed that ‘regulation of actin cytoskeleton’ and ‘focal adhesion’ were involved in the functional mechanism of ACTB in pathogenesis of cancers." (PMID 34486492, 2021). "Compared with former studies, our study challenged the common role of ACTB as a reference gene and verified its role in cancers by different databases, algorithms and experiments." (PMID 34486492, 2021). "While the expression of ACTB in cancer tissues of LUSC, PRAD (P < 0.001), BLCA and THCA (P < 0.01) is lower than the normal tissues." (PMID 34486492, 2021). "Relevance between ACTB and metastasis and invasion was identified in various types of cancers by CancerSEA." (PMID 34486492, 2021). "ACTB protein was differentially expressed in normal and cancer tissues, at higher levels in brain, liver, lung, kidney, colon, breast, pancreas, ovarian, prostate and cervical cancers." (PMID 34486492, 2021).
cancer (continued). "Our study carried out a pan-cancer analysis of ACTB based on The Cancer Genome Atlas (TCGA) and Gene Expression Omnibus (GEO) databases for the first time to explore the common role of ACTB in pan-cancer." (PMID 34486492, 2021). "To further illuminate the relationship of ACTB and immune microenvironment in cancers, we explored the correlations between ACTB and three types of immune modulators expounded in previous study on TISIDB database." (PMID 34486492, 2021). "We also applied GEPIA2 to explore the correlation of ACTB expression and the pathological stages of cancers." (PMID 34486492, 2021). "Again, stage-specific immune checkpoint analysis was conducted in the 7 cancers with stage dependency in ACTB expression." (PMID 34486492, 2021). "The genetic alteration status of ACTB in pan-cancer was explored using Cbioportal based on TCGA datasets." (PMID 34486492, 2021). "The role of ACTB in pan-cancer including expression profile, overall survival analysis, immune landscape and functional relevance was explored." (PMID 34486492, 2021). "Herein, we used the TIMER2 to explore the relationship of ACTB expression and the infiltration level of various immune cells in all TCGA cancers." (PMID 34486492, 2021). "We observed that ACTB was correlated with multiple functional states in multiple cancers, especially in HNSCC." (PMID 34486492, 2021). "We mapped the ACTB and ACTG1 mutations found in these two cancer types on the 3D-structure of actin showing they are in regions important for actin polymer formation or binding to myosin." (PMID 32349449, 2020). "A search in PubMed with the keywords ‘ACTB’ or ‘ACTG1’ and ‘mutations and cancer’ indeed yields a limited number of papers." (PMID 32349449, 2020). "One of the interesting effects we found on the Test Cancer BioChip was the suppression of anchorage-independent growth of both tested cell lines by ACTB siRNA." (PMID 23049944, 2012). "At day 10, the strongest suppression of SK-BR-3 growth on the Test Cancer BioChip was observed using siRNAs for ACTB, PIK3CA, and ERBB2." (PMID 23049944, 2012). "Some reference genes such as ACTB and B2M are expressed somewhat more in stomach tissues than in cancer cell lines." (PMID 20507635, 2010). "MHY9, INF2, FLNA, MYH10, FLNB, FLN1, and ACTB were upregulated in HNSC cancer tissues." (PMID 38584831, 2024). "However, ACTB is abnormally expressed in various cancers, altering the cytoskeleton and affecting tumor invasiveness and metastasis." (PMID 39896807, 2024). "ACTB upregulation in cancer may regulate tumor cell proliferation, phenotype, and metastasis, thereby further affecting tumor malignancy and prognosis in patients with tumor." (PMID 38649690, 2024). "Considering the special relationship between ACTB and F-actin in certain cancer cells, ACTB could emerge as a crucial target in disulfidptosis." (PMID 38739940, 2024). "Although future studies are needed to determine the role of ACTB and ACTG1 mutations as driver or passenger mutations in different cancers, our data show a possible link between impaired cytoskeletal actomyosin dynamics, cofilin-mediated actin turnover, and cancer development." (PMID 38446501, 2024). "Aberrant expression of ACTB and MYL6 is associated with invasion and metastasis in many cancers." (PMID 38116315, 2023). "Furthermore, knockdown of ACTB, which was upregulated in our rHGP cancer areas, is known to decrease expression of β-Catenin, the main nuclear effector of canonical WNT signalling." (PMID 36691028, 2023). "However, the emerging evidence suggests that ACTB expresses unstably and plays a key role in a variety of human diseases, particularly cancer." (PMID 36232605, 2022). "Considering current limited understanding of ACTB immunological relevance in cancers, our study first presented a comprehensive landscape of immune correlation of ACTB in cancers and we inferred that ACTB might be a potential target of immune therapy." (PMID 34486492, 2021).
cancer (continued). "Then, the expression of ACTB mRNA across all TCGA cancers was investigated on TIMER2." (PMID 34486492, 2021). "Most ACTB-immune checkpoint correlations showed stage dependency in one or more cancers." (PMID 34486492, 2021). "This study aimed to investigate the function and clinical significance of ACTB in pan-cancer." (PMID 34486492, 2021). "In conclusion, our first pan-cancer analyses of ACTB presented statistically significant correlations of ACTB expression with patient prognosis, immune cell infiltration, immune checkpoints, other immune modulators and functional states across different cancers." (PMID 34486492, 2021). "Thirdly, the two cancer-associated CSB mutations R1467Q and G1484R, located on the opposite side of the CSB-WHD away from its ubiquitin-binding pocket, impair RNAPII association with PPP sites of ACTB, GAPDH and RPL13A genes." (PMID 33806087, 2021). "We investigated ACTB expression in normal tissues and pan-cancer." (PMID 34486492, 2021). "Additionally, we also found positive correlation between ACTB expression and most immune modulators including many immune checkpoint molecules in pan-cancer, suggesting ACTB was synergistic with checkpoint members and other immune modulators." (PMID 34486492, 2021). "Our study indicated that ACTB may play a malignant and complicated role to be reckoned with in tumor development and its role as a housekeep and reference gene in cancer tissues and cell lines should be used with caution." (PMID 34486492, 2021). "Nevertheless, we combined ACTB-interacted proteins and ACTB-correlated genes in cancers for enrichment analysis and the latent function of “focal adhesion“, ”regulation of actin cytoskeleton” and “regulation of actin filament” in the pathogenesis of cancers was uncovered." (PMID 34486492, 2021). "Current evidence have indicated that ACTB polymerization, cytoskeleton formation and localization could drive cancer cell protrusions and motility, promoting cancer metastasis and invasiveness." (PMID 34486492, 2021). "We speculated that ACTB upregulation in cancers might regulate tumor cell proliferation, phenotype and metastasis to further influence the tumor malignancy and prognosis of tumor patients." (PMID 34486492, 2021). "ACTB was analyzed at single-cell resolution in different cancers." (PMID 34486492, 2021). "High ACTB expression was observed in corresponding cancer tissues." (PMID 34486492, 2021). "However, emerging evidence suggests that ACTB is differentially expressed and plays a crucial role in multiple human diseases, especially cancers." (PMID 34486492, 2021). "It was reported that GAPDH and ACTB were also differentially expressed in other cancer types." (PMID 17640361, 2007). "GAPDH and ACTB are most commonly used for normalization, including studies on cancer." (PMID 17640361, 2007). "Assuming that these increases may reflect the vigorous total exosome production from aggressive cancer cells as confirmed in previous studies, we adopted ACTB, which had a greater difference, as one of the candidate biomarker PEX mRNAs, and used GAPDH as the reference gene." (PMID 39867897, 2024). "We found lots of them might play a key role in the transformation of enterocyte progenitor cells to cancer cells such as MALAT1, B2M, EEF1A1, RPL5, B3GNT7, RHOB and ACTB might play a key role in the transformation of enterocyte progenitor cells to cancer cells." (PMID 36944972, 2023). "Somatic mutations of the ACTB gene associated to cancer have not been reported." (PMID 36046434, 2021). "However, despite the great resource of big clinical data, the relationship of ACTB and pan-cancer remains unknown." (PMID 34486492, 2021). "Our first pan-cancer study of ACTB offers insight into the prognostic and immunological roles of ACTB across different tumors, indicating ACTB may be a potential biomarker for poor prognosis and immune infiltration in cancers, and the role of ACTB as a reference gene in cancers was challenged." (PMID 34486492, 2021).
cancer (continued). "If the two cytoplasmic actin genes ACTB and ACTG1 are more frequently mutated in hematological malignancies than sequencing screens suggest, this should be apparent from a comparison of the alteration frequency of these two genes in blood cancers relative to other cancer types." (PMID 32349449, 2020). "Interestingly, using a novel clustering approach of rare mutations on 3D structures of proteins to distinguish non-functional passenger events from functional driver mutations, ACTB (and also ACTA2) was identified as a gene potentially involved in cancer progression." (PMID 32349449, 2020). "The RSF model identified key predictive genes including OLFML2B, ACTB, and C1QB, and demonstrated broad applicability across multiple cancer types." (PMID 39925852, 2025). "In numerous in vivo and in vitro studies, a variety of cancer-related mRNAs have been identified, including PTEN, ACTB, MAPK4, MKI67, c-MYC, and CD44." (PMID 40082414, 2025). "The PI3K-Akt signaling and proteoglycans in cancer were significantly enriched, involving proteins such as COL1A1, FN1, THBS1, FLNA, and ACTB." (PMID 40710368, 2025). "The same might hold true for components of the cytoskeleton, since TUBB, ACTB, and ACTG1 are all included in the candidate gene list, which would be in line with the frequently observed increased expression of cytoskeletal proteins in cancer and associations with poor outcome and chemoresistance." (PMID 40694850, 2025). "Total host DNA levels, measured as the number of ACTB gene copies per μL of the reaction mixture, were compared across four patient groups: NILM, LSIL, HSIL, carcinoma, and control group." (PMID 40564169, 2025). "In conclusion, our study highlights the potential of ACTB, ACTN4, INF2, and MYL6 as therapeutic targets and biomarkers for PD and cancer." (PMID 39329952, 2024). "This study found that ACTB, ACTN4, INF2, and MYL6 are closely related to PD and pan-cancer and can be used as candidate genes for the diagnosis, prognosis, and therapeutic biomarkers of neurodegenerative diseases and cancers." (PMID 39329952, 2024). "The top 5 identified genes affecting survival negatively (p < 0.05) in at least 4/9 cancer types were LOXL2, ITGA3, ACTB, EFNB2 and ITGB1." (PMID 37206618, 2023). "The quantitative analysis of the gene expression involves five reference genes (ACTB, TFRC, GAPDH, GUSB, and RPLP0) and 16 cancer-related genes." (PMID 36042999, 2022). "ACTL6A, CHD2, and ACTB had the highest pan‐cancer G‐score for amplification, whereas CHD5, SHPRH, INO80, and ACTR8 had the highest pan‐cancer G‐score for deletions." (PMID 35789070, 2022). "Several housekeeping genes, such as ACTB, TUBB1, and PTMA, as well as noncoding RNAs, such as srpRNA (RN7SL2), are highly abundant in the plasma of both cancer patients and HDs." (PMID 35816095, 2022). "We found that AS-tDR-007333 precipitated with several cancer-related RNA-binding proteins, including HSPB1, DHX9, ACTB, YBX3, and ILF2." (PMID 35526007, 2022). "The most stable expressed gene in MM cancer tissues was ACTB, with a lower average between mean SD and mean Ct (1.17 for ACTB; 1.22 for HPRT1; 1.62 for TFRC), while in CSCC cancer tissues it was TFRC (1.00 for TFRC; 1.13 for HPRT1; 1.45 for ACTB)." (PMID 34940125, 2021). "ScRNA-seq analysis from CancerSEA revealed functional relevance of ACTB with metastasis, invasion, hypoxia, differentiation and EMT in different cancers, especially in HNSCC." (PMID 34486492, 2021). "In general, the results indicated that the PARP1/ACTB and PARP2/ACTB mRNA cellular content ratios are notably increased (t-test, p < 0.001) in most cases and for all tested cancer cell lines after treatment with the alkylators ASA-A, ASA-B, ASA-C and POPA." (PMID 34440232, 2021). "As far as the inducible increases of PARP2/ACTB mRNA ratios are concerned, ASA-A, ASA-B and POPA were comparably more effective, whereas ASA-C was less effective against all tested cancer cell lines." (PMID 34440232, 2021).